ZNF304 (zinc finger protein 304)
Description:
Acts as a transcriptional regulator and plays a role in gene silencing. Probably forms a corepressor complex required for activated KRAS-mediated promoter hypermethylation and transcriptional silencing of several tumor suppressor genes (TSGs) or other tumor-related genes in colorectal cancer (CRC) cells. Also required to maintain a transcriptionally repressive state of genes in undifferentiated embryonic stem cells (ESCs) by inducing trimethylation of 'Lys-27' of histone H3 (H3K27me3) in a Polycomb group (PcG) complexes-dependent manner. Associates at promoter regions of TSGs and mediates the recruitment of the corepressor complex containing the scaffolding protein TRIM28, methyltransferase DNMT1 and histone methyltransferase SETDB1 and/or the PcG complexes at those sites. Transcription factor involved in the metastatic cascade process by inducing cell migration and proliferation and gain resistance to anoikis of ovarian carcinoma (OC) cells via integrin-mediated signaling pathways. Associates with the ITGB1 promoter and positively regulates beta-1 integrin transcription expression. Promotes angiogenesis. Promotes tumor growth.
Tractability: PROTAC: ubiquitination databases record sites on it.
Gene: Protein-coding gene on chromosome 19 (57,351,271 to 57,359,898, forward strand). Ensembl gene ENSG00000131845.
Subcellular location: Nucleus
Subcellular location (Human Protein Atlas): Nuclear speckles; Cytosol
Pathways (Reactome):
Gene expression (Transcription): Generic Transcription Pathway
Gene Ontology:
Molecular function: promoter-specific chromatin binding; protein binding; DNA-binding transcription factor activity, RNA polymerase II-specific; RNA polymerase II cis-regulatory region sequence-specific DNA binding
Biological process: DNA methylation-dependent constitutive heterochromatin formation; integrin-mediated signaling pathway; negative regulation of anoikis; negative regulation of transcription by RNA polymerase II; positive regulation of angiogenesis; positive regulation of cell migration; positive regulation of epithelial cell proliferation; positive regulation of transcription by RNA polymerase II; regulation of transcription by RNA polymerase II; positive regulation of DNA-templated transcription; regulation of DNA-templated transcription
Cellular component: nucleus
Genetic constraint (gnomAD): Loss-of-function variants: 7 observed, 8.51 expected, observed/expected ratio (o/e) 0.82, 90% interval 0.47 to 1.52. That is too few expected variants to judge how well the gene tolerates losing a copy. Missense variants: 669 observed, 844.31 expected, observed/expected ratio (o/e) 0.79, 90% interval 0.74 to 0.85. Synonymous variants: 280 observed, 287.11 expected, observed/expected ratio (o/e) 0.98, 90% interval 0.88 to 1.08.
Homologues: Orthologues: chimpanzee ZNF304 (99% identical), macaque ZNF304 (96% identical), dog ZNF304 (86% identical), rabbit ZNF304 (84% identical), pig ZNF304 (83% identical), rat Zfy1 (18% identical), tropical clawed frog zfx (18% identical), zebrafish zfx (18% identical), mouse Zfy1 (18% identical), mouse Zfy2 (17% identical). Paralogues in human: ZNF551 (46% identical), ZNF792 (45% identical), ZNF256 (45% identical), ZNF587B (44% identical), ZNF548 (42% identical), ZNF418 (40% identical), ZNF772 (40% identical), ZNF549 (39% identical), ZNF134 (38% identical), ZIK1 (36% identical), ZNF773 (36% identical), ZNF419 (35% identical), and 26 more.
Diseases named in the same sentence as ZNF304 in open-access papers:
ZNF304 is named in the same sentence as 11 diseases in open-access papers, as found by Europe PMC text mining. Sharing a sentence is not in itself a finding about the gene and the disease. The quoted sentences say what the papers report.
ovarian carcinoma (5 papers, 2016 to 2022). A malignant neoplasm originating from the surface ovarian epithelium. "In addition, an integrative bioinformatic analysis of The Cancer Genome Atlas ovarian cancer dataset and experimental validation reveals the association between ZNF304 and ovarian cancer metastasis." (PMID 27411336, 2016). "For example, overexpression of ZNF304 transcriptionally regulates β1 integrin, resulting in metastasis of ovarian cancer." (PMID 35038288, 2022). "It has been reported that ZNF304 regulated β-1 integrin expression, promotes ovarian cancer cell survival and protects against anoikis in OC." (PMID 35227285, 2022). "As one of the key anoikis players, ZNF304-integrin axis has been shown to fight against anoikis during tumor development and promote a variety of proto-cancer pathways important for cell survival, migration, and invasion in ovarian cancer." (PMID 36338978, 2022). "ZNF304 has also been reported as a regulator of the RAS pathway by recruitment of an epigenetic silencing complex in tumor suppressor genes in colorectal cancer and as a promoter of cell survival in ovarian cancer." (PMID 30938061, 2019).
clear cell renal carcinoma (2 papers, 2021 to 2023). A malignant epithelial neoplasm of the kidney characterized by the presence of lipid-containing clear cells within a vascular network. "However, the roles of transcription factor ZNF304 and its clinical significance in clear cell renal carcinoma (ccRCC) remain unclear." (PMID 34692488, 2021).
breast carcinoma (1 paper, 2019). "In the analysis for RFS, differential expression of ZNF611, ZNF304, RIPK1, DUSP8, TNFRSF21 and HRAS genes was associated with outcome for breast cancer patients who received radiotherapy." (PMID 30938061, 2019). "Therefore, we propose that the dual function of miR‐122 in the isogenic model of radioresistant breast cancer cells could be result of transcriptional reprogramming controlled by the modulation of ZNF611 and ZNF304 by miR‐122." (PMID 30938061, 2019).
colon cancer (1 paper, 2022). "DNMT1 and ZNF304 could form the complex required for tumor suppressor gene transcriptional silencing to protect colon cancer cells." (PMID 35889255, 2022).
HIV-1 infection (1 paper, 2020). The type species of lentivirus and the etiologic agent of acquired immunodeficiency syndrome (AIDS). "Further studies are required to define the precise triggers and signaling mechanism by which ZNF304 expression is induced after HIV-1 infection." (PMID 32956422, 2020).
lung adenocarcinoma (1 paper, 2023). A carcinoma that arises from the lung and is characterized by the presence of malignant glandular epithelial cells. "ZNF304 is not highly expressed in lung tumors and its expression is significantly anti-correlated with UHRF1 expression in lung adenocarcinoma patients carrying a KRAS mutation, suggesting that UHRF1 may instead mediate this phenotype in KRAS-driven lung cancer." (PMID 37407562, 2023).
ovarian tumor (1 paper, 2016). "Using delivery of ZNF304 siRNA by a dual assembly nanoparticle, these authors successfully conducted a sustained ZNF304 silencing which increased anoikis and reduced ovarian tumor growth in orthotopic mouse models." (PMID 27411336, 2016).
tumor (8 papers, 2014 to 2023). "Mutant KRAS caused an increase in the levels of these two proteins, which in turn caused the elevated ZNF304 levels and the excessive marking of the DNA in the tumor suppressor genes." (PMID 24623306, 2014). "ZNF304 (Zinc Finger Protein 304) plays a role in gene silencing, including several tumor suppressor genes, and is overexpressed in several types of cancers." (PMID 35227285, 2022). "In vivo and in vitro results indicate that overexpression of ZNF304 or targeted inhibition of miR-183-5p can effectively inhibit tumor progression." (PMID 34692488, 2021). "To investigate the expression level of ZNF304 in ccRCC, firstly, we collected clinical samples and located the ccRCC tumor and an area of normal kidney tissue by using hematoxylin and eosin staining." (PMID 34692488, 2021). "We next used a pathology tissue ChIP (PAT-ChIP) assay to measure association of ZNF304 with p14ARF, p15INK4B, and p16INK4A promoters in KRAS-positive human CRC tumor samples and, as a control, adjacent matched normal colon." (PMID 24623306, 2014). "ZNF304 is a protein that binds to stretches of DNA, including regions of DNA at the start of several tumor suppressor genes, and it recruits the enzymes that add the chemical marks that switch off these genes." (PMID 24623306, 2014). "Therefore, we believe that the downstream pathway of ZNF304 is possible as a potential anti-tumor pathway." (PMID 34692488, 2021). "Furthermore, clinicopathologic factors of ZNF304 mRNA expression level was markedly negative associated with tumor grade but not with age, sex and tumor size etc." (PMID 34692488, 2021). "The study found that the stabilization of ZNF304 by USP28 results in the hypermethylation and transcriptional silencing of tumor-suppressor genes during oncogenic transformation, consistent with the results of the physical interactions." (PMID 37450415, 2023). "In this sense, we evaluated the prognostic value of the ZNF611, ZNF304, RIPK1, TNFRSF21, DUSP8 and HRAS genes according to tumor subtypes." (PMID 30938061, 2019). "In a previous study, we have found that silencing of the Fas tumor suppressor in RAS-transformed NIH 3T3 cells requires ZFP354B, which like ZNF304 is a KRAB-ZFP protein." (PMID 24623306, 2014). "We next asked whether ZNF304 and its corepressors silenced CIMP marker genes in other KRAS-positive human CRC cell lines and tumor samples." (PMID 24623306, 2014). "In the absence of ZNF304, these tumor suppressor genes remained switched on in cancer cells with the KRAS mutation, so the growth of the tumor was slowed down." (PMID 24623306, 2014).
cancer (6 papers, 2014 to 2023). A tumor composed of atypical neoplastic, often pleomorphic cells that invade other tissues. "The findings revealed a robust physical association between USP28 and ZNF304, a key player in cancer metastasis." (PMID 37450415, 2023). "Previous studies revealed ZNF304 to be a transcriptional repressor involved in cancer cell survival." (PMID 34692488, 2021). "Our finding that ZNF304 levels are elevated in both KRAS-positive CRC cells and hESCs is consistent with studies reporting a variety of similarities between cancer cells and stem cells." (PMID 24623306, 2014). "The results from the CCLE support that the selected genes C20orf194 and ZNF304 (LIFR without data) were specifically hypermethylated and downregulated in CRC cell lines compared to those of other cancer types." (PMID 35974349, 2022).
ZNF304 also shares sentences with these, for which no sentence is quoted: colorectal cancer (2 papers); lung carcinoma (1).